FSHR (follicle stimulating hormone receptor)
Diseases named in the same sentence as FSHR in open-access papers (continued):
Sharing a sentence is not in itself a finding about the gene and the disease.
cancer (continued). "This approach still needs extensive investigation in the future and provokes extensive discussion on the development of a cancer therapies based on agents tethered to anti-FSHR antibodies." (PMID 30941099, 2019). "It is thus probably not yet time to re-write the textbooks with the functional implications of FSH/FSHR in extragonadal tissues or in cancer cells or TVECs." (PMID 30778333, 2019). "Aberrant FSHR function facilitates the development of cancer, and FSH promotes proliferation of ovarian cells." (PMID 30402135, 2018). "64Cu-labeled monoclonal antibody (mAb) used to image FSHR in tumors via PET imaging further showed the value of FSHR as a cancer tissue marker." (PMID 29097909, 2017). "If tumors were positive, in most cases, only a minor portion of the cancer cells showed FSHR expression, mainly in the cytoplasm and rarely on the plasma membrane." (PMID 31548530, 2017). "This fact strongly increases FSHR potential relevance as a clinical target for cancer imaging and for therapy, especially for tumors that are highly resistant to currently available antiangiogenic treatments." (PMID 23688201, 2013). "FSH and its corresponding receptor (FSHR) have an important function in various cancers, including prostate, endometrial and ovarian cancer." (PMID 24137476, 2013). "Additionally, FSHR expression showed significant differences between benign and malignant tumors at various grades (p < 0.05)." (PMID 40431589, 2025). "In addition to FSHR expression on GCs, FSHR has also recently been reported to be expressed on other cell-types such as pluripotent stem cells and cancer cells in multiple organs including the ovaries." (PMID 41029688, 2025). "Regarding relationships between FSHR polymorphisms and OC, the National Center for Biotechnology Information (NCBI) single nucleotide polymorphism (SNP) database has identified 731 SNPs in FSHR genes, some of which are associated with cancer susceptibility." (PMID 39741875, 2024). "By combining the extracellular domain of human tissue factor with anti-FSHR antibodies, the coagulation cascade may be activated, resulting in thrombus formation, ischemia, and cancer cell death." (PMID 37568488, 2023). "Nevertheless, FSHR is a highly promising tool in the future fight against cancer." (PMID 37568488, 2023). "This review mainly covers the connection between FSH and FSHR signaling and its role in cancer." (PMID 35002517, 2022). "FSH/FSHR signaling controls several crucial biological pathways, therefore, malfunctioning of this signaling system is bound to culminate into several disorders, including cancer." (PMID 35002517, 2022). "Thus, cancer comprises undifferentiated, primitive cells including stem cells which express abundant FSHR." (PMID 34717708, 2021). "However, direct evidence to support the concept that although FORKO mice lack FSHR, VSELs expressing FSHR are mobilized from other tissues to the ovaries and initiate cancer remains to be generated." (PMID 34717703, 2021). "The ovarian stem cells as well as the cancer cells that arise in the OSE express FSHR." (PMID 34717703, 2021). "Previous studies in HEK293N and granulosa cells support our hypothesis that low FSHR levels promote pro-tumorigenic cancer cell behaviour." (PMID 33374698, 2020). "It is also possible that FSHR may undergo a cancer induced proteolytic cleavage which has been described for other proteins." (PMID 33374698, 2020). "Non-malignant cells within cancer tissue have been shown to be devoid of FSHR expression, which implies a potential role of FSHR as a diagnostic, prognostic, or even a therapeutic tool." (PMID 30778333, 2019). "With regard to cancer cells and TVECs (primary and metastatic), it was suggested that FSHR might serve as a potential cellular marker of different tumors and provide a novel approach for targeted cancer therapy." (PMID 30778333, 2019). "We detected GNRHR in 54%, LHCGR in 77% and FSHR in 0% of the cancer samples." (PMID 30400009, 2019).
cancer (continued). "Several groups suggested that the FSHR observed in TVECs and cancer cells is functional." (PMID 30778333, 2019). "If extragonadal FSHR expression and function could be proven by additional independent studies in the TVECs, as well as in the cancer cells, the finding would suggest for FSHR a great utility as a biomarker and/or medicinal target." (PMID 30778333, 2019). "Furthermore, the recently documented roles of the FSHR in diverse extragonadal tissues, including cancer, fat metabolism, and bone density regulation, has highlighted the potential utility of LMW modulators of FSHR activity." (PMID 30728807, 2018). "In this study, 68Ga labeled FSH1 peptide was developed for imaging of FSHR in cancers." (PMID 29097913, 2017). "Aim of this study was to see whether the expression of FSHR can be useful in the differentiation of benign and malignant thyroid lesions." (PMID 25685198, 2015). "Therefore, FSHR has emerged as a potential anti-cancer therapeutic target and prognostic tool." (PMID 35002517, 2022). "Our study might contribute to the application of FSHR-based targeted therapy and imaging in cancer." (PMID 29461120, 2018). "Therefore, blocking the formation of functional shunts by inhibiting endothelial FSH/FSHR signaling may be a new strategy in cancer therapy." (PMID 25652007, 2015). "Among the analyzed cancer cell lines, only KGN and human FSHR cDNA-stably transfected HEK293 (HEK293-FSHR) cells expressed functional FSHR." (PMID 40490708, 2025). "Excessive self-renewal of VSELs results in cancer and this explains ubiquitous expression of embryonic markers including nuclear OCT-4 along with FSHR in cancerous tissues." (PMID 34717703, 2021). "FSHR receptor expression has been detected in the blood vessels of many cancers, suggesting a role for FSH and FSHR in angiogenesis, via induction of vascular endothelial growth factor (VEGF)." (PMID 33802415, 2021). "Surprisingly, the surrounding non-malignant normal cells within cancer tissue are devoid of FSHR expression." (PMID 34717708, 2021). "The discord between FSHR and LHCGR with their respective protein levels is surprising but may be due to differences in mRNA turnover in cancer cells compared to gonadal tissues, mRNA instability, or varied protein half-lives in different cell types." (PMID 33374698, 2020). "Furthermore, it has been shown that activation of FSHR triggers the PI3K/AKT/Snail signaling pathway, activates ERK1/2, and upregulates expression of OCT4, thereby promoting cancer cell epithelial–mesenchymal transition, migration, and distant invasion." (PMID 28439256, 2017). "Three different antibodies have been frequently used to study, immunohistochemically, the expression of FSHR in human tumors: sc-13935, sc-7798, and FSHR323, and are claimed to be suitable tools for immunohistochemical analysis of cancer tissues." (PMID 31548530, 2017). "These mice have endocrine profile similar to postmenopausal women, are infertile, never ovulate, and have no FSHR but still develop cancers." (PMID 23509758, 2013). "FSHR expression has been linked to angiogenic activities in epithelial and endothelial cells of the endometrium and reported to be localized to endothelial cells of cancer vasculature, although these initial reports with distinct FSHR antibodies were not confirmed in a key follow-up study." (PMID 35185785, 2021). "Overexpression of FSHR is also observed in OSE in cancer tissues as compared to normal OSE—that may activate oncogenic pathways leading to cancer." (PMID 23509758, 2013). "Similarly, detection of vascular endothelial FSHR in various types of solid tumors and sarcomas has prompted a debate as to whether an anti-FSH antibody could serve as a treatment modality in future anti-cancer drugs." (PMID 30941099, 2019).
cancer (continued). "RT-PCR analysis did not always find FSHR transcripts, and some scientists believe that the solution should be found by further investigating the expression of FSHR1 and FSHR3 isoforms and their specific role in pathological angiogenesis and cancer cell proliferation, respectively." (PMID 41024941, 2025).
infection (11 papers, 2010 to 2025). The state of being infected such as from the introduction of a foreign agent such as serum, vaccine, antigenic substance or organism. "These authors found that all the observed tissue degeneration phenotypes were fully alleviated by loss of FSHR-1, a G protein-coupled receptor required for the activation of infection and stress response genes." (PMID 35205128, 2022). "FSHR-1 is required for the survival both of infection by diverse pathogens and of xenobiotic insults that cause oxidative stress." (PMID 26360906, 2015). "Using tissue-specific knockdown, the authors demonstrated that FSHR-1 primarily acts in the intestine to regulate survival of worms during infection." (PMID 33476324, 2021). "Upon infection, the FSHR-1 pathway activates not only the expression of known infection response genes, but also a collection of stress response genes." (PMID 26360906, 2015). "We have previously shown that FSHR-1 is necessary and sufficient in the intestine for its role in promoting survival of infection by ingested pathogens." (PMID 26360906, 2015). "FSHR-1 is central not only to the worm’s survival of infection by multiple pathogens, but also to the worm’s survival of xenobiotic cadmium and oxidative stresses." (PMID 26360906, 2015). "Infected worms produce reactive oxygen species to fight off the pathogens; FSHR-1 is required at the site of infection for the expression of detoxifying genes that protect the host from collateral damage caused by this defense response." (PMID 26360906, 2015). "Upon infection, FSHR-1 activates expression of a collection of known antimicrobial infection response genes that defend the worm by attacking the pathogen." (PMID 26360906, 2015). "FSHR-1 is additionally required for the protective ability of worms to sense an infection and modify their behavior to avoid pathogens." (PMID 26360906, 2015). "FSHR-1 protects worms from toxic reactive oxygen species (ROS) and cadmium, independent of infection." (PMID 26360906, 2015). "We have shown that the FSHR-1 pathway functions in the absence of infection to promote survival of heavy metal and oxidative stress, suggesting that FSHR-1’s ligand must be endogenously produced rather than bacterial in origin." (PMID 26360906, 2015). "An intestinal role for FSHR-1 in the response to infection-induced oxidative stress is not unexpected because the worms must sense and respond to oxidative damage at the site of ROS production, the intestine." (PMID 26360906, 2015). "Whether FSHR-1 regulates the defecation motor program upon infection or oxidative stress has not yet been determined, but it is conceivable that thyrostimulin-like signaling may also regulate protective immune and stress responses in C. elegans." (PMID 37409228, 2023). "Rather than detecting physical damage as a sign of infection, it is tempting to speculate that FSHR-1 could bind an endogenously-produced DAMP that signals chemical damage caused by ROS production." (PMID 26360906, 2015). "The GPCR FSHR-1 promotes host defense across Gram-negative and Gram-positive challenges in parallel to p38, while the mitochondrial UPR regulator ATFS-1 mediates pathogen-induced mitochondrial stress to innate immunity and enhances survival under PA14 infection." (PMID 41472019, 2025).
reproductive diseases (3 papers, 2015 to 2024). "Besides in PCOS, FSHR and C9orf3 have both been identified as susceptibility genes for another reproductive disease—erectile dysfunction." (PMID 26220222, 2015). "The expression pattern at rs12478601 (THADA locus) in skin and fat, rs804279 (GATA4 locus) and rs1795379 (KRR1 locus) in fat and rs2268361 (FSHR locus) in skin predicted involvement in reproductive diseases." (PMID 28068351, 2017).
gastrointestinal tumors (1 paper, 2023). "In 2010, it was reported that FSHR can be expressed on the endothelial cells of the intratumoral and peritumoral blood vessels associated with different types of tumors, such as gastrointestinal tumors." (PMID 37568488, 2023).
kidney disease (1 paper, 2019). "To understand the roles of FSH in kidney disease, we first examined the expression of FSHR in kidney samples from normal female mice." (PMID 31243899, 2019).
FSHR also shares sentences with these, for which no sentence is quoted: benign ovarian tumors (3 papers); hypogonadotropic hypogonadism (3); cervical cancer (2); dyslipidemia (2); embryonal carcinoma (2); erectile dysfunction (2); glioma (2); mastitis (2); Prostate tumor (2); seminoma (2); Turner syndrome (2); abdominal aortic aneurysm (1); acute appendicitis (1); adrenocortical tumors (1); age-related macular degeneration (1); asthma (1); Atrophy (1); autism (1); autoimmune polyglandular syndrome (1); bacterial infection (1); benign prostatic hyperplasia (1); benign tumors (1); cardiovascular disease (1); cerebellar hemangioblastoma (1); Chagas disease (1); coronary heart disease (1); COVID-19 (1); E. coli infection (1); familial male-limited precocious puberty (1); fat (1).
A further 48 diseases each share a sentence with FSHR in 1 paper.